IL18 (interleukin 18)
Diseases named in the same sentence as IL18 in open-access papers (continued):
Sharing a sentence is not in itself a finding about the gene and the disease.
asthma (continued). "Furthermore, lack of improvement in asthma symptoms on benralizumab, an eosinophil depleting mAb was associated with raised/residual levels of IL-18 in sputum." (PMID 39554494, 2024). "The complex balance between the elements of the IL‐18 axis suggests that although IL‐18 might play a role in airway remodelling in asthma, this mechanism is likely to be quiescent in stable disease, whereas its role following an exacerbation might be more important." (PMID 34194747, 2021). "The observations that sensitization increased number of IL‐18BP+ macrophages, and that IL‐18 up‐regulated expression of IL‐18BP in lung macrophages of sensitized mice indicate that certain allergen may eliminate contribution of IL‐18 to asthma via IL‐18BP+ macrophages." (PMID 28922563, 2018). "Indeed, the ratios between plasma concentrations of IL‐18BP and IL‐18 were 1 in HC volunteers and 12.8 in patients with asthma, supporting further the fact that there is excessive amount of IL‐18BP to completely abolish actions of IL‐18 in both HC volunteers and asthmatic patients." (PMID 28922563, 2018). "Interactions between IL-18 and tryptase may contribute to mast cell recruitment in asthma." (PMID 27069315, 2016). "However, the role of IL-18 is considered controversial in some experimental mouse asthma models and it is still unknown whether overexpression of IL-18 in the lungs alters AHR and pulmonary inflammation in asthma." (PMID 23382928, 2013). "Also, anti-inflammatory cytokines such as IL-10, IL-12, IL-18, IL-21, IL-23, IL-27 and interferons may have a therapeutic potential in asthma." (PMID 18315837, 2008). "People with asthma had more NLRP3, ASC, caspase-1, and the pro-inflammatory cytokines IL-1β and IL-18 in their bronchoalveolar lavage fluid and sputum samples." (PMID 41318536, 2025). "IL‐18 is overexpressed in patients with COPD, asthma and EoE compared to healthy individuals, orchestrating both T1 and T2 inflammation." (PMID 40492692, 2025). "Monoclonal antibodies against IL-1β (Canakinumab) and IL-18 (GSK1070806) are in Phase II trials for severe neutrophilic and Th2-low asthma, respectively, providing a direct strategy to quench the inflammatory output of pyroptosis." (PMID 41394843, 2025). "In asthma models induced by tobacco extract and PM2.5, inhibiting TRPA1 can reduce the expression of IL-1β and IL-18." (PMID 39735214, 2024). "We observed that the expression of N-GSDMD, IL-18, and IL-1β was enhanced in OVA-induced asthma mouse model." (PMID 38849380, 2024). "Increased IL-18, IL-18R, eosinophils, lymphocytes, CD8+ T cells in the lung from fatal asthma group." (PMID 39554494, 2024). "The evidence linking IL-18 to both airway inflammation, mucus plugging and AHR emphasizes its significance in asthma pathogenesis." (PMID 39554494, 2024). "HDM prestimulation increased the release of IL-18, EGF, TWEAK, and M-CSF and decreased CCL3 in SARS-CoV-2-infected HBECs from patients with asthma in comparison to SARS-CoV-2 infection alone." (PMID 37087523, 2023). "Therefore, IL-18 may be a potential mediator between asthma and UC." (PMID 38162651, 2023). "The administration of MCC950 to a toluene diisocyanate-induced asthma model blocked the activation of NLRP3 and downregulated protein expression of caspase-1, IL1β, and IL18." (PMID 36189256, 2022). "In the asthma-COPD overlap, the IL-18 level tends to increase against the background of the progression of the severity of the disease." (PMID 32733164, 2020). "IL-18 knockout mice exhibited decreased neutrophilic inflammation and airway remodeling in OVA-induced asthma." (PMID 32423405, 2020). "A report that a severe IL‐18/IL‐18BP imbalance results in Th1 lymphocyte and macrophage activation in patients with secondary haemophagocytic syndrome 25 may support the view that an IL‐18/IL‐18BP imbalance decides the role of IL‐18 in the pathogenesis of asthma." (PMID 28922563, 2018).
asthma (continued). "And that if the levels of ATP are high, as described in patients with asthma and COPD, the EVs can release IL-1β and IL-18." (PMID 24972036, 2014). "However, it is unknown whether IL-18 plays any role in the pathogenesis of asthma." (PMID 23382928, 2013). "Our data shows that overproduction of IL-18 protein in the lungs increases pulmonary inflammation accompanied with IL-13 producing CD4+ T cells, and results in increasing AHR in this mouse asthma model." (PMID 23382928, 2013). "Our study showed that the ZLN005 reduced NLRP3 protein expression and IL-18 and IL-1β mRNA levels, suggesting that ZLN005 could alleviate asthma by inhibiting inflammasome activation." (PMID 40343297, 2025). "In conclusion, IL-18 is not just an ancillary cytokine in asthma but one of the key components in its pathophysiology, particularly in severe cases." (PMID 39554494, 2024). "The data from lung autopsy obtained from fatal asthma patients had significant expression of IL-18 protein and IL-18R compared to lung tissues from patients with mild asthma and “no asthma” diagnosis." (PMID 39554494, 2024). "Higher expression of NLRP3 and higher levels of IL-1β and IL-18 from severe asthma group in non-stimulated state.Significant increase of IL-1β and IL-18 after NLRP3 activation." (PMID 39554494, 2024). "Indeed, in our hands, SARS-CoV-2 infection alone led to an increased release of inflammasome-dependent and independent proinflammatory cytokines such as IL-18 and IL-33, respectively, as well as to the decrease of anti-viral CCL4 in controls and in asthma." (PMID 37087523, 2023). "Using IL1R and IL18 deficient mice and the same asthma model, it was found that the potential protective effect of NLRP1 was not related to IL1R signaling, but to IL18 since IL1R but not IL18 deficient mouse, failed to reproduce the NLRP1 deficient phenotype." (PMID 36189256, 2022). "Prior evidence suggests that expression of IL-18 pathway components, specifically IL-18R1, differs between those with asthma and those without." (PMID 34591794, 2021). "In biopsies from subjects with asthma, the IL‐18 expression was not different in the lamina propria compared with controls but was decreased in the epithelium." (PMID 34194747, 2021). "In an Aspergillus-sensitized asthma model, IL-18 was again found to be protective and acted without IL-12 or IFN-γ to enhance Aspergillus clearance." (PMID 33643264, 2021). "Given the multifaceted proinflammatory nature of IL-18 activity, the detected elevated serum concentrations of this cytokine suggest that IL-18 plays an important role in the implementation of systemic inflammation in both COPD and BA and also in the asthma-COPD overlap." (PMID 32733164, 2020). "Evaluation of changes in the mean values of IL-18 in all examined patients showed an excess of the level of this cytokine in patients with COPD, asthma-COPD overlap, and BA compared with healthy individuals by 4-4.8 times (100.5 [68.2; 123, 3 pg/ml, ANOVA p ≤ 0.0001)." (PMID 32733164, 2020). "As macrophages are the major source of IL‐18BP within the submucosa 29, it is not difficult to understand IL‐18 is unlikely to contribute to the pathogenesis of asthma through lung macrophages." (PMID 28922563, 2018). "Serum IL‐18 level was found significantly higher in children who had asthma 5, but the plasma/serum level of IL‐18BP in asthma, and correlation between IL‐18 and IL‐18BP has not been investigated." (PMID 28922563, 2018). "It was observed previously that IL-18 protein and IL-18 receptor were strongly expressed in the lungs of fatal asthma, but the correlation between IL-18 and tryptase has not been investigated before." (PMID 27069315, 2016). "Using ELISA kits, we observed that IL-18 levels in the plasma of moderate and severe but not mild asthma were elevated in comparison with HC subjects." (PMID 27069315, 2016).
asthma (continued). "IL-18 levels in patients with mycoplasmal pneumonia were significantly higher than those in control subjects, and they were lower in patients with asthma compared with patients without asthma." (PMID 26751073, 2016). "In this study, we examined whether overexpression of IL-18 protein in the lungs induces AHR and pulmonary inflammation in a mouse model of asthma." (PMID 23382928, 2013). "Overexpressing the IL-18 protein in the lungs induces type 1 and type 2 cytokines and airway inflammation, and results in increasing airway hyperresponsiveness via CD4+ T cells and IL-13 in asthma." (PMID 23382928, 2013). "Our present results suggest that overexpression of IL-18 in the lungs may induced pulmonary inflammation and AHR, and result in exacerbating the disease activities in patients with asthma." (PMID 23382928, 2013). "The serum IL-18 concentrations did not vary significantly according to asthma severity, family history of atopy, or passive smoking." (PMID 23283012, 2009). "The serum IL-18 expression did not correlate with the age, weight, and height percentiles, duration of asthma, hemoglobin concentration, or total leukocyte, eosinophil, neutrophil, lymphocyte, and monocyte counts of the patients." (PMID 23283012, 2009). "The massive IL-18 and IL-1β release from pyroptotic AECs and macrophages may influence the differentiation, proliferation and function of CD4+ T cells, and determine the course of asthma progression." (PMID 39611173, 2024). "In addition, the protein expression levels of NLRP3, caspase-1, cleaved caspase-1, GSDMD, GSDMD-N, IL-18, and IL-1β were increased, indicating that MUC1, TLR4/MyD88/NF-κB pathway, and NLRP3-induced pyroptosis are involved in the pathogenesis of asthma." (PMID 37880668, 2023). "Additionally, CAD and CAD-contained serum attenuated the up-regulated expressions of Bax, Cleaved caspase-3, NLRP3, ASC, Cleaved caspase-1, GSDMD-N, IL-18, IL-1β, TLR3, p-P65, p-IκBα, and IRF3 but increased Bcl-1 and GSDMD levels in the asthma mice and LPS-induced 16HBE cells, respectively." (PMID 36213326, 2022). "Because the protective effect of NLRP1 in asthma was independent of IL-1R signaling, we hypothesized that IL-18 plays a major role in mediating protection." (PMID 33378691, 2021). "All these factors may have contributed to donor variability in relation to asthma and responsiveness to IL‐18." (PMID 34194747, 2021). "To date, the exact role of IL-18 in asthma pathogenesis is not entirely clear." (PMID 33378691, 2021). "The patients' IL-18 levels were not influenced by the family history of atopy, inhalation corticosteroid therapy, or serum total IgE expression whether during asthma exacerbation or during stability." (PMID 23283012, 2009). "Serum IL-18 expression did not vary with the degree of asthma severity whether during exacerbation or stability." (PMID 23283012, 2009). "The serum levels of interleukin (IL)-8, IL-10, and IL-18 were examined using ELISA kits in 34 patients with M. pneumoniae infection (Group 1, 11 with severe mycoplasmal pneumonia; Group 2, 13 with mild mycoplasmal pneumonia; Group 3, 10 with asthma) and 32 age-matched, non-infected controls." (PMID 26751073, 2016). "Indeed endogenous IL-18 in experimentally induced asthma was found to be irrelevant for clinical symptoms, and therefore our finding that IL-18 may not be required to mobilize gingiva LC may possibly refer to other mucosal tissues as well." (PMID 26539556, 2015).
acute kidney injury (83 papers, 2007 to 2026). Sudden and sustained deterioration of the kidney function characterized by decreased glomerular filtration rate, increased serum creatinine or oliguria. "Excessive production of IL-18 has been associated with critical illnesses, including myocardial ischemia and acute kidney injury." (PMID 36032662, 2022). "The urinary level of IL-18 is expected to be an early diagnostic marker of acute kidney injury (AKI), and many clinical trials have been conducted." (PMID 33732720, 2021). "This study aimed to determine the diagnostic utility of sIL-18 and urine IL-18 (uIL-18) as biomarkers for acute kidney injury (AKI) and analyse the association of IL-18 polymorphisms to AKI in preterm infants." (PMID 35223418, 2021). "This study aimed to evaluate urinary neutrophil gelatinase-associated lipocalin (NGAL) and urinary interleukin-18 (IL-18) as early biomarkers of acute kidney injury in cirrhotic patients." (PMID 24967242, 2014). "Other authors have shown that parameters such as urinary neutrophil gelatinase-associated lipocalin and interleukin-18 were superior to serum Cr for acute kidney injury diagnosis." (PMID 17519026, 2007). "Urinary interleukin-18 reflects inflammasome-mediated tubular injury and, when interpreted together with neutrophil gelatinase-associated lipocalin, strengthens attribution to structural injury in cirrhosis-associated acute kidney injury." (PMID 41301868, 2025). "Inflammatory markers such as CRP, IL-6 and IL-18 have been linked to organ failure and could be indicators of acute kidney injury." (PMID 39563441, 2024). "Urine-detected IL-18 is an early diagnostic marker of acute kidney injury (AKI), and it precedes symptoms by 24–48 h." (PMID 33924469, 2021). "Simultaneously, neutrophil gelatinase-associated lipocalin (NGAL) and IL-18 have been illustrated as pivotal indicators to diagnose the acute kidney injury (AKI) early." (PMID 28222674, 2017). "The possibility that circulating IL-18 levels are predictive of renal damage has been proposed, suggesting that IL-18 may be a prognostic marker of renal involvement useful to identify patients at risk of renal failure." (PMID 27713252, 2010). "Combined with neutrophil gelatinase-associated lipocalin or interleukin-18, KIM-1 strengthens attribution to structural injury in cirrhosis-associated acute kidney injury." (PMID 41301868, 2025). "Previous studies on the pathogenesis of acute renal failure have demonstrated that NF-κB inhibitors can significantly reduce the production of IL-1β and IL-18 in albumin-stimulated HK-2 cells." (PMID 36732854, 2023). "The aim of this study was to systematically review relevant studies to evaluate the value of urinary interleukin-18 (uIL-18) in predicting acute kidney injury (AKI)." (PMID 36259446, 2022). "Renal levels of IL-1β, IL-18, and IL-6 and neutrophils have been reported to be higher in cisplatin-induced acute kidney injury." (PMID 30691208, 2019). "Here, we describe two topics of IL-18: its role in human IgA nephropathy and IL-18 as a clinical biomarker of acute kidney injury (AKI) that influences long-term outcomes of cardiac surgery." (PMID 30717382, 2019). "Recent studies have reported that urinary IL-18 can be used as early biomarkers of acute kidney injury and as a PNS activity index." (PMID 33817188, 2019). "Urinary NGAL, KIM, L FABP-1, Cystatin C, and IL18 were proposed as tools for early detection of acute kidney injury (AKI) but the determination of their validities and clinical utility is still in progress." (PMID 30643824, 2018). "Urinary IL-18 has been detected in patients suffering from acute kidney injury and is another novel marker of acute kidney injury." (PMID 30005088, 2018). "The level of interleukin-18 (IL-18), as a mediator of acute renal damage, increases in the proximal tubular epithelium in case of renal damage and acute renal failure." (PMID 29632848, 2018).
acute kidney injury (continued). "In summary, our results demonstrated that IL-18Rα-mediated signaling plays critical roles in CD4+ T-cells and APCs and was markedly faster at responding to IFN-γ and IL-18 than TLR4 stimulation in the pathogenesis of LPS-induced acute kidney injury." (PMID 29261164, 2017). "Interleukin-18 (IL-18) mediates ischemic acute tubular necrosis; it has been proved as a rapid, reliable, and affordable test marker for the early detection of acute kidney injury (AKI), but its predictive accuracy varies greatly." (PMID 24899123, 2015). "Studies have shown that IL-18 levels increase in the proximal tubular epithelium in the case of renal damage and acute renal failure." (PMID 26689528, 2015). "Recently, urinary biomarkers, such as interleukin-18 (IL-18), kidney injury molecule-1 (KIM-1), and neutrophil gelatinase-associated lipocalin (NGAL), have been used for the early detection of acute kidney injury." (PMID 24967238, 2013). "Moreover, CIS reduced serum testosterone levels and diminished testicular IL-10, as well as CIS-induced renal failure, as indicated by hypokalemia, and increased levels of creatinine, urea, sodium, IL-18, and KIM-1." (PMID 39459023, 2024). "As for the renal actions, geraniol exhibited protection against cyclosporine A-induced nephrotoxicity via lowering inflammation mediators, including (ICAM-1, IL-18, and NF-κB), protection against methotrexate-induced acute kidney injury via Keap1/Nrf2/HO-1 and MAPK/NF-κB pathways." (PMID 36009287, 2022). "In addition to inflammatory indicator, serum IL-18 has been proposed as a marker for acute kidney injury." (PMID 33915976, 2021). "The predictive ability of urinary IL-18 has also been demonstrated in critically ill children in 103 pediatric patients with renal impairment and 34 controls with normal renal function, with renal failure patients manifesting a >3 fold increase in urinary IL-18." (PMID 22131986, 2011). "Urinary interleukin-18 (IL-18) measured during the immediate postoperative period could be a promising predictor of acute kidney injury following adult cardiac surgery." (PMID 18673539, 2008). "We assessed urinary IL-18 concentration and urinary IL-18/urinary creatinine ratio in relation to the postoperative development of acute kidney injury defined as an increase in serum creatinine of greater than 50% from preoperative to postoperative peak value within 48 hours after surgery." (PMID 18673539, 2008). "Furthermore, IL-18 can be used as a biomarker for acute kidney injury, as IL-18 might be involved in the development and progression of acute kidney injury, and patients with high urine IL-18 levels benefit from anti-IL-18 treatment." (PMID 38328001, 2024). "In the present study, we investigated the association of 12 polymorphisms in six inflammatory-response genes (TNF, IL6, IL10, IL18, NFKB1 and NFKBIA) with risk of acute kidney injury (AKI) in children." (PMID 30429237, 2018). "AKI = acute kidney injury; FGF23 = fibroblast growth factor 23; uIL18 = urine interleukin 18; uNGAL = urine neutrophil gelatinase-associated lipocalin; uKIM1 = urine kidney injury molecule-1; uLFABP = urine liver-type fatty acid-binding protein." (PMID 29633705, 2018). "IL-18 is used as an early marker of renal tubular damage in acute kidney injury (AKI) in humans, and in a mouse model, IL-18 treatment worsened acute tubular necrosis." (PMID 29261164, 2017). "This study was designed to assess whether heat shock protein (Hsp72) is an early and sensitive biomarker of acute kidney injury (AKI) compared with kidney injury molecule (Kim-1), neutrophil gelatinase-associated lipocalin (NGAL), and interleukin-18 (IL-18) biomarkers." (PMID 25313566, 2014). "IL-18 (known as an interferon-gamma (IFN-γ) inducing factor), and other inflammatory cytokines have important roles in lipopolysaccharide (LPS)-induced acute kidney injury (AKI)." (PMID 29261164, 2017).